CCL5 (C-C motif chemokine ligand 5)
Diseases named in the same sentence as CCL5 in open-access papers (continued):
Sharing a sentence is not in itself a finding about the gene and the disease.
endometriosis (40 papers, 2006 to 2025). The growth of functional endometrial tissue in anatomic sites outside the uterine body. "CCL5/RANTES functions as a chemoattractant for immune cells and has been implicated in the recruitment and activation of inflammatory cells at the ectopic endometrial sites, further perpetuating the inflammatory milieu characteristic of endometriosis." (PMID 39257907, 2024). "Cytokines and inflammatory mediators such as IL-1, IL-6, IL-8, IL-12, IFN-γ, MCP-1, TNF-α, sTNFR-1, and CCL5 (RANTES), which are measured in the serum and PF of patients with endometriosis, have the potential to serve as diagnostic biomarkers in patients with endometriosis." (PMID 36865552, 2023). "SASP gene products identified by RNAseq include many inflammatory biomarkers that have been historically analyzed in endometriosis, including IL-1β, IL-6, IL-8, CCL5, TNF-α, CCL2, MMP3, HMGB1, p16, and p21." (PMID 38879630, 2024). "Not only IL‐16, but also IL‐8 and Regulated on Activation, Normal T Cell Expressed and Secreted (RANTES or CCL5) are increased in peritoneal fluid of women with endometriosis." (PMID 39110084, 2024). "Chemokines, like C-C motif chemokine ligand 2 (CCL2) and 5 (CCL5) which play a pivotal role in macrophage recruitment, are significantly increased in endometriosis lesions." (PMID 37447296, 2023). "CCL5 is responsible for the chemotaxis of T cells and some other leukocyte populations and is considered to play a part in the pathogenesis of endometriosis." (PMID 34360900, 2021). "This endometriosis animal model showed a human endometriosis phenotype, such as increased expression levels of Er-β, Ccl2, Ccl5, and Il-6." (PMID 33339236, 2020). "Cysteine–Cysteine Chemokine Receptor 5 (CCR5) and its ligand, CCL5, could drive the progression of endometriosis by increasing the accumulation of MDSC." (PMID 40508002, 2025). "IL-4 present in human ovarian endometriomas can stimulate the proliferation of endometrial stromal cells, while the CCL5/CCR5 axis may promote endometriosis progression via T-cell suppression and recruitment of CCR5+ myeloid-derived suppressor cells." (PMID 39385609, 2024). "Additionally, the CCL5, also referred to as regulated upon activation normal T-cell expressed and secreted (RANTES), has been observed to be markedly increased in both endometrial tissues and follicular fluid of women with endometriosis." (PMID 39257907, 2024). "Moreover, LUT can also regulate several signal transduction pathways, including NF-κB, AP1 and JAK–STAT, and it can inhibit macrophage recruitment to the endometriotic lesions by suppressing the secretion of CCL2 and CCL5 by endometriosis cells." (PMID 37447296, 2023). "Immune cells, such as neutrophils and macrophages, exhibit heightened activity in the context of endometriosis, while chemokines like RANTES (CCL5) further intensify inflammation by recruiting additional immune cells." (PMID 40725782, 2025). "Studies have demonstrated that endometriotic tissues in endometriosis exhibit increased production of chemokines, including C‐C motif chemokine ligand 2 (CCL2) and CCL5." (PMID 39803270, 2025). "Elevated IL-8, C-C chemokine RANTES (CCL5), MCP-1, and MIF attracted more cells in advanced endometriosis lesions in humans and mice." (PMID 40508002, 2025). "Higher levels of inflammatory mediators such as tumor necrosis factor α (TNFα), interleukins, prostaglandin E2 (PGE2), nerve growth factor (NGF) and chemokine RANTES/CCL5 were found in lesions and perioneal fluid of endometriosis patients." (PMID 40948761, 2025). "Certain chemokines, especially CXCL8 (IL-8), CCL-2 (MCP-1), and CCL5 (RANTES), can serve as biomarkers identifying patients with endometriosis, but the accuracy of such tests can be improved by including other noninflammatory markers in the biomarker panel." (PMID 27294113, 2016).
ZIKV infection (39 papers, 2017 to 2025). "However, without ZIKV disease or persistence models, it remains unclear how ZIKV infection of IFNAR-deficient mice can be used to study interdependent CCL5 responses that impact immune cell targeting and viral persistence and spread to neuronal compartments." (PMID 34399621, 2021). "Among the inflammatory mediators induced by ZIKV infection in the brain, the chemokine Ccl5/Rantes showed the highest expression, suggesting a key role in recruiting immune cells to this tissue." (PMID 41362627, 2025). "In patients with acute ZIKV infection, high levels of CCL5/RANTES have been reported to be linked to specific clinical symptoms." (PMID 38839691, 2024). "In fact, increased protein levels of RANTES/CCL5 and VEGF receptor (VEGF-R) have been detected in human placentas with ZIKV infection and their expression are associated with vascular permeability." (PMID 36315601, 2022). "Consistent with this, exogenous CCL5 addition to CCL5-KO hBMECs dose-dependently rescued ZIKV infection, hBMEC viability, and viral persistence." (PMID 34399621, 2021). "In contrast, ZIKV infection of CCL5-KO hBMECs resulted in a 30% reduction in viable CCL5-KO hBMECs at 1 dpi and a dramatic 85% reduction in viable ZIKV-infected hBMECs at 3 dpi." (PMID 34399621, 2021). "We previously reported that ZIKV infection highly induces CCL5 transcripts and CCL5 secretion from hBMECs." (PMID 34399621, 2021). "A recent study has shown that acute ZIKV infection is associated with a peak of CXCL10 and CCL5 production, in infected patients." (PMID 31282298, 2019). "Top selected ZIKV infection-associated genes from RPE cells are shown in a heatmap that includes multiple immune response genes, such as CCL5, CXCL11, CXCL1, IFNB1, IL6 and TNFSF10." (PMID 30046058, 2018). "Intriguingly, we detected the chemokines Cxcl10 and Ccl5 among genes upregulated by ZIKV infection." (PMID 33440758, 2021). "The unique high level of CCL5 expression distinguishes ZIKV infection of hBMECs and may play a key role in ZIKV persistence." (PMID 34399621, 2021). "As CCL5-KO hBMECs are eliminated by ZIKV infection, and exogenous CCL5 addition restores the viability of ZIKV-infected CCL5-KO cells, our findings support a novel role for ZIKV-elicited CCL5 as a required survival factor that permits ZIKV to persist in hBMECs." (PMID 34399621, 2021). "Finally, as demonstrated during 1-MT treatment, intracranial ZIKV infection also led to increased production of inflammatory mediators, such as CCL5 and CXCL1 in both WT and IDO-1-/- ZIKV mice." (PMID 34335614, 2021). "Furthermore, we found strong correlations between TNF-a and CCL5 concentrations and the percentages of circulating neutrophils and lymphocytes in acute ZIKV infection." (PMID 29768624, 2018). "Importantly, in all cases, the upregulation of these antiviral genes was stronger following USUV than ZIKV infection, up to 100 times for the chemokines CCL5, CXCL10 and for the IFN-Β." (PMID 28873445, 2017). "Although the half-life of CCL5 on the surface of ECs is only 30 min, constitutive CCL5 secretion during persistent ZIKV infection of hBMECs may traffic immune cells to the BBB, and both foster ZIKV’s spread to neurons and inflammatory CNS pathology." (PMID 28698279, 2017). "In the present study, we show that CXCL10 and CCL5 expression is strongly upregulated, particularly in infected undifferentiated hNPCs, suggesting that ZIKV infection induces a strong inflammatory response, which could lead to an immunocytoxic effect, particularly in undifferentiated cells." (PMID 31282298, 2019). "ZIKV infection increases the levels of a series of cytokines (IL-1α, IL-6, IL-9, IL-10, IL-12p70, and IFN-γ) and chemokines (CCL2, CCL3, CCL4, CCL5, CCL11, and CXCL1) in mouse brain." (PMID 34399779, 2021). "Daily CCL5 neutralization decreased the number of ZIKV-infected hBMECs by only 20%, while neutralizing antibodies to CCR3/CCR5 receptors reduced ZIKV infection by 50% compared to controls." (PMID 34399621, 2021).
ZIKV infection (continued). "We show that ZIKV infection activates proinflammatory (IL-1β) cytokines as well as chemokines (CCL2, CCL5, GM-CSF, G-CSF, CXCL1, and CXCL12) in the endothelial cells." (PMID 31249527, 2019). "ZIKV infection of HBMECs and RECs led to activation of several proinflammatory cytokines including IL-6, CCL1, and CCL5." (PMID 31249527, 2019). "Increased serum concentrations of both CXCL (CXCL8 and CXCL10) and CCL chemokines (CCL2, CCL3, CCL4, CCL5, and CCL11) were found in acute ZIKV infection." (PMID 29768624, 2018). "Importantly, CCL2, CCL5, CXCL9, and CXCL10 were consistently elevated in both serum and heart tissue, indicating a systemic and localized inflammatory response induced by ZIKV infection." (PMID 40762502, 2025). "In addition, CCL5 levels were elevated at the 96-hpi timepoint in HCMV infections, albeit less than those seen during ZIKV infection." (PMID 38440980, 2024). "To determine the effects of CCL5 on hBMECs, we first determined whether neutralizing antibodies to CCL5, CCR3, or CCR5 altered ZIKV infection and hBMEC viability." (PMID 34399621, 2021). "CCL5/CCR5 activation of ERK1/2 plays a prominent role in cancer cell survival and suggests an angiogenic mechanism for EC survival and barrier functions during persistent ZIKV infection (35, 61, –, 66)." (PMID 34399621, 2021). "Neutralizing antibodies to CCL5, CCR3, or CCR5 inhibited persistent ZIKV infection of hBMECs." (PMID 34399621, 2021). "Acutely infected cells produced high levels of pro-inflammatory chemokines, including CCL2, CCL3, CCL4, CCL5 and CXCL8, which could contribute to CNS inflammation during ZIKV infection in vivo by promoting the recruitment of various leukocytes into the CNS." (PMID 32375993, 2020). "HBCA infection with another flavivirus, Zika virus, is associated with only limited activation of immune cytokine/chemokine response, but ZIKV infection induces the highest upregulation of CXCL10, IL-6, 8, 12, and CCL5 (RANTES), which corresponds with the observations in TBEV-infected HBCA." (PMID 31699097, 2019). "This study noted the induction of ATF3, EGR1, JUNB, IRF7, ISG15, HERC5/6, additional ISGs, chemokines CCL5 and CXCL10, prosurvival responses, and decreased proapoptotic genes, similar to gene induction levels we found to be induced by ZIKV infection of hBMECs (GEO GSE98889)." (PMID 28698279, 2017). "Additionally, we established that cross-reactive DENV antibodies enhance ZIKV infection in KU812 cells, which is selectively coupled to enhanced chemokine ligand 5 (CCL5), interleukin 1β (IL-1β), and C-X-C motif chemokine ligand 10 (CXCL10) secretion and inhibited granzyme B (GrB) secretion." (PMID 35862953, 2022). "Here, we establish that CCL5 production is strongly coupled to enhanced ZIKV infection by nonneutralizing DENV antibodies and offer further support for selective CCL5 secretion as a consequence of immune response to Flaviviruses." (PMID 35862953, 2022). "While knockout (KO) of CCL5 failed to prevent ZIKV infection of hBMECs, at 3 days postinfection (dpi), we observed a >90% reduction in ZIKV-infected CCL5-KO hBMECs and a multilog reduction in ZIKV titers." (PMID 34399621, 2021).
colitis (38 papers, 2012 to 2026). Inflammation of the colon. "Using the dextran sulfate sodium salt (DSS)-induced UC model and CCL5 knockout (Ccl5-KO) mice, we demonstrated that CCL5 deficiency exacerbates intestinal inflammation during the acute phase of colitis, partly due to impaired interleukin-33 (IL-33)-induced Treg formation." (PMID 41433131, 2026). "To substantiate these findings, we further showed that mice deficient in CCL5 or CXCL10 could ameliorate the in vivo pathogenesis of colitis and CRC." (PMID 40749055, 2025). "To determine whether CCL5 and CXCL10 are required for DSS-induced colitis, we obtained WT, Ccl5- and Cxcl10-deficient mice from the Jackson Laboratory and treated them with 5% DSS." (PMID 40749055, 2025). "The chemokine CCL5, which stimulates inflammation and epithelial cell proliferation through the IL-6 pathway, is expressed by the microbiota and is linked to both colitis and colitis-associated carcinogenesis." (PMID 38248332, 2024). "In a second approach, we tested two CCR5 antagonists (MVC and CCL5 5p12 5m) in the chemically induced colitis context." (PMID 36341422, 2022). "In the colitis group fed with feed containing high-molar-mass oat beta-glucan (βGh+), a higher expression of CCL5 was observed compared to the control group (HβG−) and the colitis group fed with feed without beta-glucan (βG−)." (PMID 35163326, 2022). "Herein, the elevated expression of the chemokines Mcp1 and Ccl5 was suppressed by C. butyricum pretreatment, contributing to ameliorated mucosal inflammation and reduced histological damage scores in colitis." (PMID 35762770, 2022). "This makes CCL5 an excellent potential therapeutic molecule to test on animal colitis models despite the possibility of pro-allergic physiology." (PMID 30037025, 2018). "Our analysis resulted in identifying three new therapeutic targets towards ameliorating colitis: CCL5, CXCL11, and CCL17." (PMID 30037025, 2018). "We show that both Ccl5−/− and Cxcl10−/− mice are more resistant to DSS-induced colitis than WT mice by reducing immune cell infiltration, thus maintaining intestinal epithelial barrier function, consistent with previous reports that CCL5 is highly induced and plays a key role in DSS colitis model." (PMID 40749055, 2025). "Thus, the increase in CCL5 observed at 7 days after TNBS administration in colitis rats consuming feed with high-molar-mass oat beta-glucan (βGh+) appears to be beneficial." (PMID 35163326, 2022). "In this study, we analyzed whether there are interactions between the periostin and the CCL5:CCR5 systems in chemically induced colitis." (PMID 36341422, 2022). "The absence of periostin as well as the treatment with MVC results in a reduced weight loss and better clinical colitis scoring, while CCL5 5p12 5m does not." (PMID 36341422, 2022). "After 7 days of induced colitis, upregulation of the expression of 22 genes (Ccl2, Ccl3, Ccl4, Ccl5, Ccl6, Ccl7, Ccl12, Ccl17, Cxcl1, Cxcl2, Cxcl6, Cxcl9, Cxcl11, Ccr1, Ccr2, Ccr3, Ccr5, Ccr8, Cxcr2, Csf3, Osm, and Spp1) was observed in the CβG− group compared to the HβG- control group." (PMID 35163326, 2022). "After 3 days of induced colitis, the expression of CCL5 was significantly higher in the CβG− group compared to CβGl+ and CβGh+ groups, whereas statistically significant lower expression of this chemokine was observed in CβGl+ and CβGh+ groups compared to the control group (HβG−)." (PMID 35163326, 2022). "We found that there were 15 analytes upregulated in both DSS and C. rodentium colitis, including innate immune cell-associated cytokines (G-CSF, IL-1β, TNF-α, LIF, and IL-6), chemokines (CCL2, CCL5, CCL11, CXCL2, CXCL8, CXCL9, MIP-1α, and MIP-1β), and Th1 (IFN-γ) and Th17 (IL-17) cytokines." (PMID 30972302, 2019). "EtOH and DSS-colitis also elevated mRNA for CCL5 and MCP1 genes in the colon." (PMID 30389960, 2018). "EtOH and DSS-colitis also elevated mRNA for CCL5 and MCP1 genes." (PMID 30389960, 2018).
colitis (continued). "Given the essential role of CCL5 and CXCL10 in TH17-mediated protection in colitis models, their absence in mice is expected to diminish the therapeutic efficacy of TH17 adoptive cell therapy." (PMID 40749055, 2025). "CCL5 production can be induced by the microbiota in other murine models, notably exacerbating inflammation during DSS colitis." (PMID 38589975, 2024). "Transcription levels of Cxcl9, Ccl3, Ccl4, and Ccl5, which facilitate effector CD8+ T-cell extravasation into tissues, were significantly lower in the tumors of colitis mice than in that of normal mice." (PMID 37605139, 2023). "The expression of Il1a, Ccl5, Il1b, Ccl3, and Cxcl1 were significantly elevated in CD45+ cells from Il17b-/- colitis mice (P < 0.05)." (PMID 36814913, 2023). "RT-PCR results revealed a substantial upregulation of immune-related genes, such as F4/80, T-bet, MCP1, and Ccl5 in the colonic tissues of colitis mice, while CD206 showed a tendency towards a decrease in the colon of colitis mice." (PMID 37774039, 2023). "In the colitis group, the expression of CXCL1 was lower and the expression of CCL5 and CXCR2 was higher compared to the control group." (PMID 35163326, 2022). "The significance in the gene and protein expression of CCL5 changes were also confirmed by the results of the FLD analysis, which clearly confirmed the direction of changes observed after 7 days of colitis induction." (PMID 35163326, 2022). "Patients with IBD have increased CCL2 expression level, and CCL5 attracts CCR1 and CCR5-expressing inflammatory cells into colon tissue of trinitrobenzene sulphonic acid (TNBS)-induced colitis mice model." (PMID 36518763, 2022). "Both CCL5 and CXCL11 are satisfactory therapeutic molecule candidates to test initially on animal colitis models." (PMID 30037025, 2018). "Mice colonised with P. copri showed more severe colitis when exposed to dextran sulfate sodium (DSS), probably mediated via induction of the cytokine CCL5, which exaggerates DSS-induced colitis." (PMID 27885053, 2017). "In addition, the mRNA levels of proinflammatory cytokines including Ccl5, IL-17, IL-6, TNF-α, IFN-γ, CXCL10, and Ccl8 were all found to be increased in colitis tissues of S100A4Smad4-/- mice compared with those in Smad4fl/fl mice." (PMID 39664586, 2024). "Importantly, we found that growth factors (GFs) like VEGF, IGF, and PDGF as well as chemo-cytokines CCL2, CCL3, CCL4, CCL5, and CCL20 were significantly upregulated in colitis’s colonic tissues." (PMID 37691056, 2023). "The characteristic alteration of NLRP6 deficiency in mouse colonic epithelial cells is that exposure to DSS worsens colitis, and the resultant increased abundance of phylum Bacteroidetes (Prevotellaceae) can produce DSS-induced colitis by inducing CCL5 in neonatal or adult wild-type mice." (PMID 37389342, 2023). "Only after 7 days of TNBS administration, the gene expression of Ccl5 was increased in the colitis group receiving feed without beta-glucan (βG−) compared to the control group (HβG−)." (PMID 35163326, 2022). "While CCL5 and CXCL11 are good therapeutic chemokine candidates to be exogenously administered, CCL17 is a good candidate chemokine to competitively inhibit or limit colitis pathology." (PMID 30037025, 2018). "In addition, the colitis induced a significant increase in the chemokines CCL4 and CCL5, although without significant differences between the Mcpt-4fl/fl and Mcpt-4ΔCre colitis mice." (PMID 40697820, 2025). "The results showed that acute and pre-remission stages of colitis were characterized by the increased gene expression of seven chemokines and four chemokine receptors in the colon wall as well as disrupted protein expression of CXCL1, CCL5, CXCR2, CCR5, and OPN in the mucosa." (PMID 35163326, 2022).